WNT8A (Wnt family member 8A)
Description:
Ligand for members of the frizzled family of seven transmembrane receptors. Plays a role in embryonic patterning.
Synonyms: WNT8D
Tractability: Small molecule: a structure with a bound ligand is known. Antibody: UniProt places it where antibodies can reach, with high confidence; its Gene Ontology location is reachable by antibodies, with high confidence; UniProt predicts a signal peptide or a membrane-spanning region.
Gene: Protein-coding gene on chromosome 5 (138,083,990 to 138,092,365, forward strand). Ensembl gene ENSG00000061492.
Subcellular location: Secreted, extracellular space, extracellular matrix; Secreted
Pathways (Reactome):
Signal Transduction: Class B/2 (Secretin family receptors); Disassembly of the destruction complex and recruitment of AXIN to the membrane; TCF dependent signaling in response to WNT; WNT ligand biogenesis and trafficking
Gene Ontology:
Molecular function: receptor ligand activity; cytokine activity; frizzled binding; signaling receptor binding
Biological process: canonical Wnt signaling pathway; secondary palate development; anterior/posterior axis specification; cell fate commitment; dorsal/ventral axis specification; neural crest cell fate commitment; neuron differentiation; positive regulation of transcription by RNA polymerase II; response to retinoic acid; Wnt signaling pathway
Cellular component: extracellular region; extracellular matrix
Genetic constraint (gnomAD): Loss-of-function variants: 14 observed, 20.8 expected, observed/expected ratio (o/e) 0.67, 90% interval 0.44 to 1.05. The upper end of that interval is the gene's LOEUF score, 1.05, which puts it in group 4 of 6, group 1 being the genes least tolerant of losing a copy. Missense variants: 348 observed, 434.87 expected, observed/expected ratio (o/e) 0.8, 90% interval 0.73 to 0.87. Synonymous variants: 149 observed, 159.39 expected, observed/expected ratio (o/e) 0.93, 90% interval 0.82 to 1.07.
Homologues: Orthologues: chimpanzee WNT8A (99% identical), macaque WNT8A (95% identical), pig WNT8A (92% identical), dog WNT8A (84% identical), rabbit WNT8A (83% identical), guinea pig WNT8A (76% identical), rat Wnt8a (75% identical), mouse Wnt8a (74% identical), tropical clawed frog wnt8a (67% identical), zebrafish wnt8a (64% identical), zebrafish wnt8a (59% identical), Drosophila melanogaster Wnt5 (35% identical), and 5 more. Paralogues in human: WNT8B (59% identical), WNT2B (37% identical), WNT2 (35% identical), WNT4 (35% identical), WNT1 (34% identical), WNT5B (34% identical), WNT5A (34% identical), WNT3A (33% identical), WNT3 (33% identical), WNT10A (32% identical), WNT7B (31% identical), WNT16 (31% identical), and 6 more.
Diseases named in the same sentence as WNT8A in open-access papers:
WNT8A is named in the same sentence as 14 diseases in open-access papers, as found by Europe PMC text mining. Sharing a sentence is not in itself a finding about the gene and the disease. The quoted sentences say what the papers report.
gastric cancer (4 papers, 2022 to 2024). A primary or metastatic malignant neoplasm involving the stomach. "Similarly, the lipid-modified Wnt proteins Wnt8a and Wnt3 are disseminated by cytonemes in zebrafish and gastric cancer cells, respectively." (PMID 38123680, 2024). "Interestingly, we could not detect the actin motor myosin 10 (MYO10), which regulates the formation and elongation of filopodia on WNT7A-positive dendritic filopodia, suggesting a difference from the Wnt8a cytonemes observed in zebrafish gastrulation or WNT3 cytonemes in human gastric cancer." (PMID 39576204, 2024).
germ cell tumor (2 papers, 2021 to 2022). A benign or malignant, gonadal or extragonadal neoplasm that originates from germ cells. "Gene‐based analyses identified significant associations between tinnitus and WNT8A (p = 2.5 × 10−6), encoding a signaling protein important in germ cell tumors." (PMID 35322580, 2022). "WNT8A encodes a protein of the WNT gene family and may be involved in the development of early embryos and germ cell tumors." (PMID 34454438, 2021).
atrial fibrillation (1 paper, 2021). A disorder characterized by an electrocardiographic finding of a supraventricular arrhythmia characterized by the replacement of consistent P waves by rapid oscillations or fibrillatory waves that vary in size, shape and timing and are accompanied by an irregular ventricular response. "Additionally, a recent genome-wide association study showed that WNT8A was associated with atrial fibrillation." (PMID 35187114, 2021).
hearing loss (1 paper, 2022). "Genetics variants in TXNRD1 and WNT8A are notable risk factors for hearing loss and tinnitus, respectively." (PMID 35322580, 2022).
ovarian carcinoma (1 paper, 2009). A malignant neoplasm originating from the surface ovarian epithelium. "Likewise, the role of WNT3 and WNT8A in ovarian cancer needs to be further addressed." (PMID 19849863, 2009).
Tinnitus (1 paper, 2022). Tinnitus is an auditory perception that can be described as the experience of sound, in the ear or in the head, in the absence of external acoustic stimulation. "In addition, gene‐based association analysis identified WNT8A significantly associated with tinnitus." (PMID 35322580, 2022). "For the first time, we identified WNT8A to be genome‐wide significant for tinnitus and TXNRD1 as having borderline genome‐wide significance for hearing loss following cisplatin treatment through a gene‐based association analysis." (PMID 35322580, 2022). "No SNPs met genome‐wide significance in the GWAS of tinnitus; however, gene‐based association analysis identified WNT8A as genome‐wide significant (p = 2.5 × 10−6)." (PMID 35322580, 2022). "Nevertheless, the role WNT8A in relation to tinnitus and/or de novo tinnitus is not yet established." (PMID 35322580, 2022).
cancer (6 papers, 2009 to 2024). A tumor composed of atypical neoplastic, often pleomorphic cells that invade other tissues. "Cancer development was observed by the modulation of genes involved in cell death (HIST1H1T, CASP14, and DNAJC3), cancer related genes (WNT8A and CASC8), gene expression (transcription) (ZNF570 and ZFP42), and metabolism of proteins (CALB2 and KLHDC3)." (PMID 31797963, 2019). "In addition, after exposure to TiO2 MPs, DEG related to cancer, cell death, and gene transcription were observed like WNT8A and CASC8 which are highly correlated with CRC development and progression." (PMID 31797963, 2019). "E2F1 and E2F4 chromatin immunoprecipitation sequencing (ChIP-seq) data analyses from cancer cells (E2F1 ChIP-seq, E2F4 ChIP-seq, RBL2/p13055) further indicated the binding of E2F1 and E2F4 in the proximity of WNT4 and WNT8A." (PMID 37725511, 2023).
tumor (2 papers, 2019). "Expression levels the remaining Wnt ligands, including Wnt1, Wnt3, Wnt4, Wnt5A, Wnt8A, Wnt9B, Wnt10A and Wnt16, remained insignificantly different between liver tumors tissues and adjacent non-tumor tissues." (PMID 30814912, 2019).
WNT8A also shares sentences with these, for which no sentence is quoted: pancreatic cancer (3 papers); basal cell carcinoma (1); colorectal cancer (1); glioblastoma multiforme (1); glioma (1); osteoarthritis (1).